PRL (prolactin)
Diseases named in the same sentence as PRL in open-access papers (continued):
Sharing a sentence is not in itself a finding about the gene and the disease.
hypothyroidism (continued). "Moreover, hypothyroidism leads to a decrease in dopamine inhibitory effect on pituitary cells leading to increased PRL synthesis." (PMID 39754184, 2025). "Finally, 6 (28.6%) had an idiopathic hPRL, despite complete investigations (PRL chromatography, pituitary MRI, hypothyroidism, pregnancy, hPRL drugs) and a careful analysis of their medical files." (PMID 35250884, 2022). "The workup showed hyponatremia (118 mEq/l), secondary hypothyroidism, and low prolactin levels." (PMID 36465526, 2022). "Our patient’s serum prolactin was in the range associated with drug effect or hypothyroidism, which was not present." (PMID 29568783, 2018). "Biochemical severity of hypothyroidism did not predict coexistence of other hormone deficiencies; however, three males exhibited subnormal/borderline basal prolactin." (PMID 30086211, 2018). "However, prolactin levels have rarely been investigated in children with hypothyroidism, especially in those with ScH." (PMID 28529200, 2017). "Hypothyroidism causes an increase in the levels of thyroid releasing hormone (TRH) which in turn stimulates secretion of thyroid stimulating hormone (TSH) and prolactin (PRL) and PRL inhibits the synthesis and secretion of gonadotrophins." (PMID 28723963, 2017). "Hypothyroidism may cause pituitary and thyrotrophic hyperplasia which result in elevated TRH and prolactin release." (PMID 26091810, 2015). "In contrast, elevated TRH can increase levels of TSH and PRL in patients with hypothyroidism." (PMID 26091810, 2015). "On the other hand, since the increase in ERβ mRNA was observed on P, before the increase in PRL and E2, it may be a direct effect of hypothyroidism and have a role in the subsequent increase in circulating E2 and PRL." (PMID 20149258, 2010). "In addition, a variety of physiological (intense exercise, acute stress, sleep, sexual arousal, etc.)and pathological conditions (prolactinomas, hypothyroidism, hepatic dysfunction, PCOS, etc.)can cause lactotrophic cells to increase their PRL secretion, possibly leading to HPRL." (PMID 38004264, 2023). "Likewise, our study revealed age-related changes in PRL levels, indicating that age is important because concomitant drug use and illnesses such as hypothyroidism and the degeneration of the ovarian secretion function, may be common in elderly populations." (PMID 36313772, 2022). "In addition, Mittra and colleagues hypothesized that circulating TH could regulate the mammotropic effects of PRL and that the increase of PRL activity occurring in the hypothyroidism condition might lead to dysplasia and eventually neoplasia of breast cells." (PMID 35207645, 2022). "Among the endocrine features, patients with primary overt hypothyroidism may have mild increase in total testosterone (T) and free testosterone (fT) total and free estradiol, prolactin (PRL) and luteinizing hormone (LH), and decreased sex hormone binding globulin (SHBG) levels." (PMID 28868249, 2017). "Inhibition of hypothalamic dopamine in hypothyroidism could also increase PRL secretion." (PMID 26421010, 2015). "In turn, prolactin levels were higher in women with than without thyroid hypofunction, and this difference was particularly pronounced in the overt disease, which is in agreement with the commonly accepted view that hypothyroidism is one of the causative factors for prolactin excess." (PMID 40428279, 2025). "The elevated basal PRL levels and the very low TSH levels despite the severe hypothyroidism in the second case were also considered findings indicative of isolated TSH deficiency." (PMID 28515030, 2017). "Although there were no overt endocrine symptoms, hormonal evaluation revealed hypothyroidism and growth hormone axis suppression, along with elevated prolactin levels due to pituitary stalk effect." (PMID 40599421, 2025). "In other words, in hypothyroidism, the concentrations of both TSH and PRL increases." (PMID 34305584, 2021).
hypothyroidism (continued). "Hypothyroidism must also be evaluated for, as TRH stimulates prolactin secretion." (PMID 27446618, 2016). "Our here reported results are indirectly also supported by previous reports on negative impact of hypothyroidism on prolactin, gonadotropin releasing hormone and sex steroid levels." (PMID 27165095, 2016). "Pathogenic pathway of shock, hypoglycaemia and hyponatremia was thus related to hypocortisolism, anaemia and thrombocytopenia secondary to hypothyroidism, amenorrhoea due to low gonadotropins, and other non-specific features secondary to low prolactin levels and hypothyroidism." (PMID 36062035, 2022). "Hypothyroidism removes the negative feedback on hypothalamic TRH and subsequently may cause an increase in prolactin secretion." (PMID 25518745, 2014). "Although PRLRlong mRNA content was not modified by hypothyroidism, the elevated circulating PRL concentrations may be responsible for the high ERβ mRNA content found on E." (PMID 20149258, 2010). "Hypothyroidism increases Thyrotropin Releasing Hormone (TRH) transcription and secretion from the hypothalamus but in healthy pre-menopausal women hypophyseal stimulation by TRH of only TSH, LH and prolactin, but not of FSH, was observed." (PMID 36005590, 2022).
hyperprolactinaemia (82 papers, 1992 to 2026). "Firstly, considering that increased cardiometabolic risk is a characteristic feature of prolactin excess, our findings provide arguments that the association between prolactin levels and cardiometabolic complications may be U-shaped." (PMID 39456268, 2024). "In turn, similar baseline and follow-up levels of cardiometabolic risk factors in women declining pharmacotherapy of iatrogenic prolactin excess and in untreated women with normal prolactin levels argue against adaptive changes in response to prolactin excess." (PMID 37176648, 2023). "Prolactin-lowering properties of metformin seem particularly important in case of iatrogenic prolactin excess, which can be very difficult to treat." (PMID 37297964, 2023). "Fourth, the treatment of patients with both prolactin excess and thyroiditis may be very difficult because the prolactin-lowering effects of cabergoline in this group are weak." (PMID 39204081, 2024). "Thus, only high-dose metformin should be recommended to reduce prolactin levels in subjects with prolactin excess." (PMID 39204081, 2024). "Secondly, assessment of prolactin concentration and hsCRP during the follow-up may provide an indirect insight into the cardiometabolic effects of cabergoline in females with coexistent prolactin excess and thyroid autoimmunity." (PMID 39852352, 2025). "Recently, we have encountered several cases of elevated (above the upper limit of normal (ULN) of the institutional RI) prolactin levels in women without clinical signs of prolactin excess, all measured with the Elecsys prolactin assay on the Cobas (Roche Diagnostics)." (PMID 39422626, 2024).
sexual dysfunction (79 papers, 2008 to 2025). Disturbances in sexual desire and the psychophysiologic changes that characterize the sexual response cycle and cause marked distress and interpersonal difficulty. "It is well known that low prolactin levels are associated with decreased sexual desire, sexual dysfunction, and reduced quality of life." (PMID 39361237, 2025). "The concept of low circulating PRL levels as a clinical syndrome appeared for the first time in 2009 in association with sexual dysfunction in which male patients with PRL serum levels b5 μg/L showed a higher risk of MS." (PMID 40894210, 2025). "An analysis in males with sexual dysfunction showed that PRL levels in the lowest quartile (˂5 ng/ml) were associated with a higher prevalence of MetS." (PMID 39172174, 2024). "Contrasting those reports, in middle-aged and elderly male patients lower circulating prolactin levels were associated with the metabolic syndrome, major cardiovascular events and sexual dysfunction." (PMID 39304061, 2024). "Cross-sectional studies have shown an association between low levels of PRL and the development of metabolic syndrome (including type 2 diabetes) and sexual dysfunction in middle-aged and older men, including one study from EMAS." (PMID 38829475, 2024). "The definition of hypoprolactinemia first appeared in 2009, when a study on male patients with sexual dysfunction detected a higher risk of MetS in patients with PRL levels <5 μg/L, particularly middle-aged and elderly men." (PMID 36237192, 2022). "The relationship between APDs and sexual dysfunction is mediated in part by antipsychotic blockade of pituitary dopamine D2 receptors causing increased prolactin secretion." (PMID 36430171, 2022). "Chlorpromazine (CPZ), an antipsychotic drug, is associated with increasedrisk of sexual dysfunction through increasing prolactin levels." (PMID 26644861, 2015). "Potential causes include nonadherence to treatment, low quality of life associated with sexual dysfunction or increased rates of depression and anxiety associated with prolactin elevation effects." (PMID 23968123, 2013). "Among those, the only large-scaled study was conducted in 2,351 male patients with sexual dysfunction, in whom low PRL concentrations were associated with an increased number of MetS factors." (PMID 23517652, 2013). "Use of this category of medication can increase prolactin levels and place the patient at risk for sexual dysfunction and lower bone mineral density." (PMID 23853622, 2012). "Clinical studies have demonstrated that with the exception of risperidone, atypical antipsychotics have significantly less impact on serum prolactin compared with conventional antipsychotics, and are also less likely to cause sexual dysfunction." (PMID 19102734, 2008). "Low PRL levels may indeed be associated with sexual dysfunction, and this association could be partially explained by increased dopaminergic tone and a low central serotonin tone." (PMID 38700812, 2024). "Fourth, our economic analysis omitted common side effects of antipsychotic treatment that may cause impairments in quality of life (eg, sexual dysfunction, increase in prolactin levels, and cardiovascular and gastrointestinal side effects)." (PMID 37600505, 2023). "The increase in prolactin caused by antipsychotic drugs may lead to irregular menstruation in women and sexual dysfunction in men, affecting patient compliance." (PMID 37821875, 2023). "The increase of prolactin caused by antipsychotic drugs may cause irregular menstruation in women and sexual dysfunction in men, affecting patients' compliance." (PMID 36061293, 2022). "Postsynaptic dopamine blockade, prolactin elevation, and α1-receptor antagonism might be the underlying mechanisms in the pathogenesis of antipsychotic-induced sexual dysfunction." (PMID 34421613, 2021).
sexual dysfunction (continued). "Antipsychotic drugs can cause sexual dysfunction by increasing the level of prolactin, on the other hand, the antidopaminergic mechanism of action of antipsychotic drugs itself may contribute to suppressing the reward system and reducing sexual desire." (PMID 34681171, 2021). "Antipsychotic drugs with high D2-binding affinity have been identified as more likely to cause sexual dysfunction and risperidone may be associated with higher prolactin elevation than other SGAs." (PMID 22937269, 2011). "Incorporating prolactin levels as a secondary outcome, the study provides insight into potential mechanisms linking antipsychotic induced alterations of prolactin levels to sexual dysfunction." (PMID 40839626, 2025). "Females are more likely to experience elevated blood prolactin and weight increase, whereas males are more prone to sexual dysfunction." (PMID 39833706, 2025). "The primary outcome is the overall prevalence of sexual dysfunction among patients undergoing antipsychotic treatment, while the secondary outcomes include the domains of sexual dysfunction (e.g., desire, arousal, orgasm) and serum prolactin levels." (PMID 40839626, 2025). "Among men consulted for sexual dysfunction, those with prolactin levels in the lowest quartile were characterized by the highest risk of metabolic syndrome and lowest penile vascular flow." (PMID 39456268, 2024). "In a study carried out in pre- and post-menopausal normoprolactinemic women consulting for sexual dysfunction, those with the lowest PRL levels complained of poorer sexual desire than those with the highest PRL levels." (PMID 39172174, 2024). "The recognition of the role played by low prolactin levels in the context of sexual dysfunction in both men and women is highly important." (PMID 39425884, 2024). "Clinical assessments and further research are usually necessary to better understand the specific mechanisms and implications of low PRL levels on sexual dysfunction." (PMID 38700812, 2024). "A similar definition of hypoprolactinemia (PRL < 5 ng/ml) was also proposed by Corona and co-authors in a study on male patients with sexual dysfunction." (PMID 39172174, 2024). "Higher rates of sexual dysfunction in females in form of decreased vaginal lubrication can be explained in terms of the greater effect of antipsychotic medication on the prolactin levels of women than men." (PMID 37720899, 2023). "Partner’s sexual dysfunction (as perceived by the patient) was more common in FSD normo-PRL (32%) than in FSD hyper-PRL women (7.7%)." (PMID 37204690, 2023). "Reducing prolactin also helps with sexual dysfunction and fertility in premenopausal women and helps to prevent osteoporosis after menopause." (PMID 37759839, 2023). "Conversely, a higher prevalence of MetS was observed in middle-aged and elderly male patients with sexual dysfunction and PRL levels <5 μg/L." (PMID 36237192, 2022). "Increased prolactin levels were found in 9%, dyskinesia in 5%, sexual dysfunction in 5%, and sedation in 14% during the first day after the injection." (PMID 34840286, 2022). "Female participants recorded higher levels of sexual dysfunction than their male counterparts did, whereas male participants had comparatively lower prolactin levels and lower rates of spousal partnership." (PMID 34421613, 2021). "Male participants also recorded lower ASEX scores, lower prevalence of sexual dysfunction, lower prolactin levels, lower glucose levels, lower HDL-C levels, larger waist circumferences, and higher blood pressure values." (PMID 34421613, 2021). "Hyperglycemia can result in elevated serum prolactin levels and lead to neurotransmitter changes, which are potentially related to sexual dysfunction." (PMID 31783733, 2019). "In 42 patients administered 200 mg/day gradually increased to 800 mg/day CBD or amisulpride over 28 days, there were significantly fewer CBD-related AEs compared to amisulpride, including lower prolactin release, and less sexual dysfunction." (PMID 31161980, 2019).
sexual dysfunction (continued). "Other studies have had variable results for correlational type analyses but most generally report higher rates of sexual dysfunction and menstrual disturbances with higher prolactin levels." (PMID 23968123, 2013). "There is evidence that sildenafil is able to address such antipsychotic related sexual dysfunction in men including those patients who also report raised serum prolactin levels." (PMID 19102734, 2008). "Additionally, the analysis will explore the relationship between prolactin levels and sexual dysfunction." (PMID 40839626, 2025). "Antipsychotics thought to affect the sexual response cycle directly through antagonistic effects on the dopamine system (e.g., desire, arousal, and orgasm) and indirectly contribute to sexual dysfunction (e.g., through weight gain, anticholinergic effects and elevated prolactin levels)." (PMID 40839626, 2025). "In other populations, dopamine agonists have proven helpful in the reduction of prolactin and the improvement of sexual desire and function, and may also provide some benefit for the management of sexual dysfunction in females living with CKD." (PMID 39273752, 2024). "When adjusting the differences between FSD hyper-PRL and FSD normo-PRL women for partner’s sexual dysfunction, graduation and current use of hormonal replacement therapy, only that in Desire retained statistical significance (F = 7.172, p = 0.008 for Desire; F = 0.377, p = 0.540 for Satisfaction)." (PMID 37204690, 2023). "It is proposed that prolactin elevation might reduce sex hormone release via an alteration of the hypothalamic–pituitary–gonadal axis, and consequently lead to sexual dysfunction." (PMID 34421613, 2021). "This drug increased PRL levels, yet some reports have shown that the switch from risperidone or paliperidone ER to paliperidone palmitate treatment (PP, an intramuscular depot formulation) reduced PRL concentration as well as sexual dysfunction, a common PRL-RAE." (PMID 32373066, 2020). "The serum prolactin level was significantly higher in patients who reported at least 1 sexual dysfunction item than in those who did not; therefore, the serum prolactin level should be measured in patients who complain of sexual dysfunction." (PMID 29209406, 2017). "The present study found that the serum prolactin level increased in the sexual dysfunction group." (PMID 29209406, 2017). "An interesting aspect in this study was that quetiapine had overtaken risperidone in the frequency of sexual dysfunction, although risperidone caused the highest levels of prolactin elevation and quetiapine caused none." (PMID 20048451, 2009). "By systematically comparing the sexual side effects and prolactin-related impacts of various antipsychotics, this study aims to provide clinicians with evidence-based guidance for selecting medications that minimize sexual dysfunction, a key factor affecting patient adherence." (PMID 40839626, 2025). "The effect of prolactin on sexual dysfunction may be influenced by increased dopaminergic tone." (PMID 39425884, 2024). "Studies have shown that sexual dysfunction may be related to elevated PRL levels." (PMID 34285917, 2021). "Notably, the serum prolactin level may have increased in patients complaining of sexual dysfunction." (PMID 29209406, 2017). "The initial model included the following determinants: age, estradiol, prolactin, TSH and BDI-II, with the diagnosis of sexual dysfunction as a dependent variable (total FSFI score: ≤ 26.55, positive diagnosis; > 26.55, negative diagnosis)." (PMID 33478026, 2021). "Fifteen years ago, we originally described a male phenotype of hypoprolactinemia in a cohort of 2,531 men consulting for sexual dysfunction selected for being without hyperprolactinemia (PRL > 35 ng/mL) or pituitary disorders." (PMID 39066947, 2024). "The lower prolactin levels in male participants might partially explain their lower ASEX scores and rates of sexual dysfunction." (PMID 34421613, 2021).